MRM1 (mitochondrial rRNA methyltransferase 1)
Description:
S-adenosyl-L-methionine-dependent 2'-O-ribose methyltransferase that catalyzes the formation of 2'-O-methylguanosine at position 1145 (Gm1145) in the 16S mitochondrial large subunit ribosomal RNA (mtLSU rRNA), a universally conserved modification in the peptidyl transferase domain of the mtLSU rRNA.
Synonyms: FLJ22578
Tractability: PROTAC: its protein half-life has been measured.
Target class: Enzyme; Transferase
Gene: Protein-coding gene on chromosome 17 (36,601,583 to 36,608,971, forward strand). Ensembl gene ENSG00000278619.
Subcellular location: Mitochondrion matrix
Subcellular location (Human Protein Atlas): Mitochondria
Pathways (Reactome):
Metabolism of RNA: rRNA modification in the mitochondrion
Gene Ontology:
Molecular function: protein binding; RNA binding; rRNA (guanosine-2'-O-)-methyltransferase activity; rRNA (guanine) methyltransferase activity; methyltransferase activity; RNA 2'-O-methyltransferase activity; RNA methyltransferase activity; S-adenosylmethionine-dependent methyltransferase activity
Biological process: rRNA processing; rRNA 2'-O-methylation; rRNA modification; RNA processing; rRNA methylation
Cellular component: mitochondrial matrix; mitochondrion; cytoplasm
Genetic constraint (gnomAD): Loss-of-function variants: 24 observed, 25.6 expected, observed/expected ratio (o/e) 0.94, 90% interval 0.68 to 1.32. The upper end of that interval is the gene's LOEUF score, 1.32, which puts it in group 5 of 6, group 1 being the genes least tolerant of losing a copy. Missense variants: 431 observed, 466.42 expected, observed/expected ratio (o/e) 0.92, 90% interval 0.85 to 1. Synonymous variants: 188 observed, 202.07 expected, observed/expected ratio (o/e) 0.93, 90% interval 0.82 to 1.05.
Homologues: Orthologues: chimpanzee MRM1 (99% identical), macaque DHRS11 (88% identical), dog MRM1 (80% identical), guinea pig MRM1 (79% identical), rabbit MRM1 (75% identical), mouse Mrm1 (73% identical), pig MRM1 (73% identical), rat Mrm1 (72% identical), zebrafish mrm1 (29% identical), Caenorhabditis elegans Y45F3A.9 (22% identical). Paralogues in human: TARBP1 (21% identical), MRM3 (18% identical).
Diseases named in the same sentence as MRM1 in open-access papers:
MRM1 is named in the same sentence as 2 diseases in open-access papers, as found by Europe PMC text mining. Sharing a sentence is not in itself a finding about the gene and the disease. The quoted sentences say what the papers report.
Cerebral ischemia (1 paper, 2016). Restriction of arterial blood supply to the brain associated with insufficient oxygenation to support the metabolic requirements of the tissue. "Compared with the vehicle group, Mrm1 mRNA was significantly up-regulated by BA and down-regulated by CA (P<0.01), while the associations between Mrm1 and cerebral ischemia have not been previously reported." (PMID 27383195, 2016).
glioma (1 paper, 2021). A benign or malignant brain and spinal cord tumor that arises from glial cells (astrocytes, oligodendrocytes, ependymal cells). "Our findings revealed that MRM2, NSUN4, TFB1M, and TRMT2B were correlated significantly with most immunomodulators in glioma, whereas MRM1 and RPUSD4 were correlated negatively." (PMID 34566979, 2021). "Moreover, we observed protein expression of MRM1, MRM3, TRMT2B, and NSUN4 to be significantly different between low- and high-grade gliomas, whereas other regulators could not be obtained due to lack of data." (PMID 34566979, 2021).